ACE (angiotensin I converting enzyme)
Diseases named in the same sentence as ACE in open-access papers (continued):
Sharing a sentence is not in itself a finding about the gene and the disease.
Hypertension (continued). "Presently used synthetic drugs for hypertension management, such as captopril, alacepril, lisinopril, and enalapril, are mostly ACE inhibitors, and aliskiren is the only synthetic renin inhibitor approved by the FDA for managing hypertension." (PMID 39000571, 2024). "For instance, the peptide KYIPIQ exhibits potent ACE-inhibitory activity with an IC50 value of 7.28 uM, suggesting its potential as an adjunctive therapy for hypertension." (PMID 39201758, 2024). "Cardiovascular disease (CVD) associated with COVID-19 is likely a consequence of the dysregulation of the ACE/ACE2 system, first due to SARS-CoV-2 infection but exacerbated by comorbidities such as hypertension." (PMID 39189008, 2024). "Gitelman and Bartter patients have higher expression of ACE2 and Ang 1–7, which is also an effect of ACE inhibitors/Angiotensin II receptor blockers, thus supporting the RASi protective effect in SARS-CoV-2 infection in patients with hypertension or diabetes." (PMID 38666806, 2024). "Further activation of the ACE/ANGII/AT1R axis under these conditions, especially in the vascular endothelium, aggravates hypertension characteristic of obesity and IR." (PMID 38323106, 2024). "That improving HA function in SHR in late adulthood with an ACE inhibitor improved hippocampal perfusion and restored long-term memory function, without improving working memory, suggests that hypertension-induced HA dysfunction may play a causal role in hippocampal-dependent memory decline and VCI." (PMID 37817376, 2024). "For example, peptides derived from red and brown algae have shown potential in regulating blood pressure by promoting vasodilation through the inhibition of angiotensin-converting enzyme (ACE), a common mechanism in hypertension treatments." (PMID 39728125, 2024). "The study discovered that the primary bioactivity is the inhibition of ACE, followed by the inhibition of DPP-IV and DPP-III, which are targets for treating hypertension and type-2 diabetes." (PMID 39452081, 2024). "In the succeeding paragraphs, we highlight the pertinent findings of renin, AGT and ACE SNPs in relation to PE, PIH and hypertension." (PMID 38411777, 2024). "The <1 kDa fraction, in particular, which displayed significant ACE-inhibitory and antioxidant activities, could be considered a particularly promising candidate for further development as a multifunctional therapeutic agent for hypertension and oxidative stress-related conditions." (PMID 39796337, 2024). "Food-derived angiotensin-I-converting enzyme (ACE)-inhibitory peptides have gained attention for their potent and safe treatment of hypertensive disorders." (PMID 38474646, 2024). "The presence of ACE and the (pro)renin receptor in the collecting duct further supports the contribution of the RAS toward the progression of high blood pressure and tissue fibrosis in diabetic kidneys." (PMID 38203807, 2024). "We compared the IgAN patients to a preserved renal function control group, and we found a significant difference in average blood pressure, the incidence of hypertension, eGFR, SI, PWVao, Aix, MAU, and the use of ACE inhibitors." (PMID 37661275, 2023). "A shifted balance between ACE and ACE2 towards ACE promotes angiotensin II effects on the cardiovascular system such as vasoconstriction, hypertension, and cardiac hypertrophy." (PMID 36769331, 2023). "The angiotensin-converting enzyme (ACE) plays a vital role in the induction of elevated blood pressure in vivo and is a drug target for the treatment of hypertension." (PMID 37761171, 2023). "As a critical regulator of blood pressure, the angiotensin-converting enzyme (ACE) has been identified as the severe acute respiratory syndrome coronavirus (SARS-CoV) binding site, making hypertension the most prevalent comorbidity." (PMID 37283598, 2023). "Since CGM and CPH demonstrate weaker ACE inhibitory activity than SP and SPH, it is postulated that combinations of SPH and CPH can produce improved hypertension property." (PMID 36911847, 2023).
Hypertension (continued). "The discovery might lead to an ACE gene genotype that might be used as a biomarker for the likelihood of obesity, dyslipidemia, and type 2 diabetes mellitus among hypertensive patients for the early detection and prevention of hypertension-related comorbidities." (PMID 37200278, 2023). "Our study went one step further to show that perinatal use of taurine can protect offspring from hypertension along with restoring the expression of renin, AGT, ACE, and AT1R induced by maternal CKD." (PMID 38136178, 2023). "Captopril (Ctl), as one of the angiotensin-converting enzyme (ACE) inhibitors, is widely used in the treatment of hypertension, congestive heart failure, myocardial infarction, and kidney problems caused by diabetes." (PMID 37175061, 2023). "One aspect concerns inhibition by hydrolysates of angiotensin I-converting enzyme (ACE), involved in regulation of hypertension, acting as a catalyst for converting Angiotensin-I to Angiotensin-II, a potent vasoconstrictor peptide modulating blood pressure." (PMID 36678334, 2023). "The low globulin group had higher proportions of using ACE inhibitors/ARB, ESA, and calcium channel blocker, and having hypertension compared with the high globulin group." (PMID 36670150, 2023). "Angiotensin-converting enzyme inhibitors (ACE inhibitors) and angiotensin receptor blockers (ARBs) are pharmacological agents for managing hypertension and heart failure." (PMID 37900498, 2023). "ACE inhibitors and Angiotensin receptor blocker (ARB) drugs are widely used to treat congestive cardiac failure and hypertension in adult patients." (PMID 37189632, 2023). "In comparison, there are approximately 120 times more peptides with validated anti-angiotensin converting enzyme (anti-ACE) activity; ACE is a therapeutic target for the control of hypertension." (PMID 37508348, 2023). "For instance, the ACE D allele causes an increase in ACE1 level and a decrease in ACE2 level, causing an increased level of angiotensin-2 which may predispose the individual to a variety of disorders including obesity, hypertension, increased cardiovascular risk, and thrombophilia." (PMID 36644496, 2023). "Several classes of antihypertensive drugs such as angiotensin-converting enzyme inhibitors (ACE inhibitors), calcium channel blockers, and beta blockers are used in the management of hypertension." (PMID 36860368, 2023). "For each indication (patients with hypertension, coronary artery disease (CAD), atrial fibrillation (AF), and heart failure), the supporting evidence for beta-blockers and ACE inhibitors is presented." (PMID 34533690, 2023). "Calcium channel blockers, angiotensin-converting enzyme (ACE) inhibitors, and angiotensin receptor blockers are commonly prescribed to manage hypertension." (PMID 37972000, 2023). "Angiotensin-converting enzyme inhibitors (ACE-Is) were the most commonly used agents for treating heart failure and hypertension induced by antineoplastic mAbs." (PMID 37749652, 2023). "ACE inhibitors/ARB and SGLT2 inhibitors act on hemodynamic factors, such as arterial hypertension and also SGLT2 inhibitors improve glycemic control." (PMID 36719097, 2023). "By targeting RAAS, angiotensin-converting enzyme (ACE) inhibitors, angiotensin type 1 (AT1) receptor antagonists, and aldosterone receptor blockers have been used successfully in the treatment of hypertension." (PMID 37111357, 2023). "Renin, ACE-1 and AT1R mRNA expression were significantly higher in patients with obesity and hypertension." (PMID 36973648, 2023). "In contrast, the administration of an H2S donor inhibited ACE expression in the kidney from SHR and prevented the development of hypertension." (PMID 37875978, 2023). "Black pepper (Piper guineense) seed EO was tested for its antioxidant capabilities and its influence on α-glucosidase, α-amylase, and angiotensin-I converting enzyme (ACE), three critical enzymes connected to both T2DM and hypertension." (PMID 38003691, 2023).
Hypertension (continued). "Considering that blockade of the RAS has a vasodilatory effect, our data agree with prior research demonstrating that AC has ACE inhibitory activity, by which AC treatment protected juvenile CKD rats against hypertension in this model." (PMID 37960279, 2023). "Brain ACE2 works in concert with the other RAS molecules (ACE, ANG II, and AT1R) to protect autonomic and baroreflex function, release nitric oxide, reduce oxidative stress, and prevent the onset of attenuated hypertension." (PMID 37153428, 2023). "It was found to be highly expressed in the interstitial tissue of SHR and amplifies hypertension in SHR by activating KLF5 to secrete several enzymes and growth factors, such as ACE." (PMID 36653797, 2023). "Angiotensin-converting enzyme (ACE) inhibitors and angiotensin receptor blockers (ARBs) are commonly prescribed to individuals diagnosed with diabetes and hypertension to mitigate proteinuria and decelerate the advancement of kidney disease." (PMID 37868469, 2023). "This study aims to determine the effect of genetic variations in the ACE (rs4331) and ACE2 (rs2074192) genes with hypertension comorbidity on the severity of COVID-19 in the Indonesian population." (PMID 37667339, 2023). "The most increased ACE-inhibitory activity is because the peptides made by alcalase are resistant to gastrointestinal proteases, thus absorbed in the small intestine, suggesting that these peptides could be used in the food industry to help people with high blood pressure." (PMID 36985395, 2023). "It is used as an angiotensin-converting enzyme (ACE) inhibitor, which is long-acting in treating high blood pressure, and heart failure." (PMID 36923897, 2023). "This study found hypertension, duration of IDDM, drinking, triglycerides, ACE inhibitors, LDL, age, and smoking habits as the most significant predictors for CKD prediction in T1DM patients." (PMID 36143293, 2022). "Another positive property of Abigenol®/AlbiPhenol® was highlighted in cardiomyocytes cell model H9c2, where the maximum non-toxic concentration was able to significantly reduce ACE activity because in vivo this could be associated with a decrease in hypertension risk." (PMID 35453303, 2022). "The authors determined the competitive ACE inhibitory pattern using Lineweaver–Burk plots, and the inhibitory activity has an IC50 value of 0.04 mg; the peptide inhibits hypertension in spontaneously hypertensive rats (dosage 1 mg kg−1)." (PMID 35202112, 2022). "For the management of hypertension in the HCV patient, ACE inhibitors should be given in combination with glecaprevir/pibrentasvir (GLE/PIB)” was inappropriate, with the other statements being appropriate." (PMID 36498521, 2022). "The average age of the study population was correlated with high prevalence of hypertension, and antihypertensive medications, including BB, CCB, ARBs, thiazides and ACE inhibitors can influence CO in several mechanisms." (PMID 35869445, 2022). "Research has shown increased ACE activity in both heart and aortic tissue in L-NAME hypertension, demonstrating a relationship between ACE activity and NO synthesis in this model of hypertension." (PMID 36310604, 2022). "Enalapril (ELP) is an angiotensin-converting enzyme (ACE) inhibitor, which is commonly employed for the treatment of cardiovascular diseases, including hypertension and heart failure." (PMID 35052872, 2022). "This protein binds the ACE/Ang II/Ang II receptor type 1 (AT1R), resulting in vasoconstriction, hypertension, and inflammation." (PMID 35769458, 2022). "Enalaprilat, an angiotensin-converting enzyme (ACE) inhibitor, is an active metabolite of enalapril prodrug and is used for the treatment of hypertension, heart failure, and chronic renal diseases." (PMID 36298705, 2022). "As both hypertension and T2DM are increasing global threats to human health, a lot of research has been focused on finding inhibitors for ACE or DPP4." (PMID 36360120, 2022).
Hypertension (continued). "Following the peptide chemical synthesis, the authors determined the ACE inhibitory activity with an IC50 value of 0.19 mg/mL, and H. marmoreus H2O extract is able to inhibit hypertension in spontaneously hypertensive rats." (PMID 35202112, 2022). "Maternal high-fructose diet-induced hypertension is relevant to the aberrant activation of RAS, represented by increases in (pro)renin receptor, angiotensinogen, and angiotensin-converting enzyme (ACE) in the kidneys (minocycline)." (PMID 35268005, 2022). "In brief, BAC targets ACE/ACE2 to enhance endothelium-dependent vasorelaxation and reduce vascular inflammation to attenuate hypertension as a potential modulator of the renin–angiotensin system." (PMID 35359841, 2022). "In this study, we found the inhibitory effect of ACE and DPP 4 of the leech, which is new evidence that can explain why leeches can treat hypertension and type 2 diabetes." (PMID 36080189, 2022). "In hypertensive rats, treatment with ACE inhibitor increases AMPK phosphorylation, which in turn prevents hypertension." (PMID 36431802, 2022). "Angiotensin-converting enzyme (ACE) is an ideal target for the treatment of diseases such as hypertension, heart failure, diabetes mellitus and hypertension." (PMID 36547889, 2022). "One is the classical axis that composed of ACE, Ang-2 and AT1, which can activate various cellular functions and signaling pathways related to hypertension and tissue damage." (PMID 35993052, 2022). "ACE = angiotensin-converting enzyme; ARB = angiotensin II receptor blocker; CKD = chronic kidney disease; HTN = hypertension." (PMID 35142281, 2022). "ACE Inhibitor (ACEI) and angiotensin receptor blocking (ARB) drugs, which are used commonly for hypertension as in our patient, upregulate ACE‐2 expression that can potentially increase the vascular entry of and injury by SARS‐CoV‐2." (PMID 35356160, 2022). "For patients with new-onset VSPi-induced hypertension, the current guidelines recommend medications targeting the renin–angiotensin–aldosterone (RAAS) pathway such as ACE inhibitors, ARBs, and dihydropyridine CCBs as first-line therapy." (PMID 35201530, 2022). "On the other hand, the discovery that leech extract has ACE and DPP4 inhibitory activity provides new evidence for treating hypertension and diabetes with the traditional Chinese medicine leech." (PMID 36080189, 2022). "Angiotensin-converting enzyme (ACE) inhibitors are one of the most active classes for cardiovascular diseases and hypertension treatment." (PMID 36432059, 2022). "In the PPI network, a total of 14 targets, such as TNF, CHRM1, ACE, IL10, PTGS2, REN, and F2, were the hub targets of MVO for treating hypertension." (PMID 35308213, 2022). "In the gene expression signature for hypertension, ADRB1 and ACE were both upregulated, as expected." (PMID 35013250, 2022). "Angiotensin-converting enzyme (ACE) inhibitors are a commonly prescribed class of medication used to treat heart failure, hypertension, and chronic kidney disease." (PMID 36046424, 2022). "Angiotensin-converting-enzyme (ACE) inhibitors and angiotensin II blockers are considered first-line therapy in hypertension in the setting of native CKD and also in kidney transplant recipients." (PMID 36132582, 2022). "Besides, it was reported that LVMI might be greater in the presence of ACE- DD and AGTR1-AC/CC polymorphisms in endurance athletes, which indicates that AGTR-1 polymorphisms promote LVH not only in patients with hypertension but also in healthy individuals with elevated LVMI." (PMID 36577936, 2022). "Treatment with either angiotensin-converting enzyme (ACE) 1 inhibitor, captopril, or ACE2 activator, diminazene, abolished the HEM-induced sensitization of hypertension." (PMID 35069977, 2022). "In several animal models of the fetal programming of hypertension (FPH), BP rise is controlled by treatment with ACE inhibitors or Ang II receptor antagonists similar to what occurs in essential hypertension." (PMID 35163158, 2022).
Hypertension (continued). "BAC targets ACE/ACE2 to enhance endothelium-dependent vasorelaxation and reduce vascular inflammation to attenuate hypertension as a potential modulator of the renin–angiotensin system." (PMID 35359841, 2022). "Drugs like ACE-2 inhibitors and ARBs were administered to patients with CVS disorders, including congestive heart failure and hypertension." (PMID 35165505, 2022). "Through the inhibition of the angiotensin-converting enzyme (ACE) and selective antagonism of Ang II receptors, its main use is the reduction of blood pressure in patients with arterial hypertension." (PMID 36672525, 2022). "Inhibition of angiotensin I-converting enzyme (ACE, EC 3.4.15.1) activity is a practical therapeutic approach to combat hypertensive disorders." (PMID 37430944, 2022). "There was a negative additive interaction between ACE2 G8790A and CYP11B2-344T/C on EH (U3 = − 2.221, P = 0.026, and S = 0.128) and a positive multiplicative interaction between ACE I/D and CYP11B2-344T/C on essential hypertension (P = 0.041)." (PMID 35130889, 2022). "Cilazapril is a commercially available angiotensin-converting enzyme inhibitor (ACE inhibitor; ACEI) used for the treatment of high blood pressure and heart failure." (PMID 35883443, 2022). "Enzymes include angiotensin-I-converting enzyme (ACE-1; EC 3.4.15.1) and renin (EC 3.4.23.15), which operate within the renin–angiotensin–aldosterone (RAAS) system and control high blood pressure and salt-water balance." (PMID 35206049, 2022). "In addition, the ACE/AngII/AT1R axis also has a potent inflammatory and pro-fibrotic role and triggers important adverse reactions such as myocardial hypertrophy and dysfunction, endothelial dysfunction, obesity-associated hypertension, interstitial fibrosis, and oxidative stress." (PMID 33824998, 2021). "National and international guidelines recommend angiotensin-converting enzyme (ACE) inhibitors or angiotensin receptor blockers (ARBs), calcium channel blockers (CCBs), diuretics, and beta-blockers for the management of hypertension." (PMID 34963839, 2021). "There was no significant number of hypertensive older adults who fell when taking an angiotensin-converting enzyme (ACE) inhibitor, angiotensin receptor blockers (ARB) or an alpha blocker as their hypertension medicine." (PMID 34444005, 2021). "Furthermore, the intake of Lactobacillus casei could prevent metabolic-related hypertension in perinatal rats by decreasing the Firmicutes to Bacteroidetes ratio and the expression of angiotensin-converting enzyme (ACE), while increasing Akkermansia and Lactobacillus abundances." (PMID 34579087, 2021). "A great proportion of adults with hypertension, diabetes Mellitus and/or chronic kidney disease (CKD) are currently treated with angiotensin-converting enzyme (ACE) inhibitors or angiotensin II receptor blockers." (PMID 34300311, 2021). "The utilized keywords for engine searching are “ACE inhibitors”, “Angiotensin Receptor Blockers”, “Outcome”, “COVID-19”, “SARS-COV-2”, and “Hypertension”." (PMID 33544293, 2021). "Several antihypertensive agents including angiotensin II receptor blockers (ARBs) and angiotensin-converting enzyme (ACE) inhibitors acts by blocking the RAS and are widely used in the management of hypertension." (PMID 34108047, 2021). "For COVID-19 patients with existing hypertension, the key targets and drugs are losartan, saralasin, telmisartan for targets AGTR1, AGTR2, and captopril for ACE and REN." (PMID 34067609, 2021). "Angiotensin-converting enzyme (ACE, EC 3.4.15.1) and dipeptidyl peptidase-IV (DPP-IV, EC 3.4.14.5) are crucial enzymes involved in hypertension and diabetes, respectively." (PMID 34066103, 2021). "Our previous work showed DMF administration in pregnancy protects adult offspring against hypertension programmed by antenatal DEX plus postnatal high-fat diet, which was relevant to downregulated mRNA expression of renin, AGT, ACE, and AT1R." (PMID 33669059, 2021).